RNU6-470P (RNA, U6 small nuclear 470, pseudogene)
Gene: Small nuclear RNA gene on chromosome 17 (43,412,427 to 43,412,530, forward strand). Ensembl gene ENSG00000251763.
Homologues: Orthologues: chimpanzee U6 (99% identical), macaque U6 (99% identical), mouse Gm24099 (85% identical), dog U6 (84% identical). Paralogues in human: RNU6-116P (89% identical), RNU6-1316P (88% identical), RNU6-33P (88% identical), RNU6-47P (88% identical), RNU6-698P (88% identical), RNU6-1 (88% identical), RNU6-1060P (88% identical), RNU6-1145P (88% identical), RNU6-1175P (88% identical), RNU6-1227P (88% identical), RNU6-15P (88% identical), RNU6-19P (88% identical), and 1289 more.